TNC (tenascin C)
Description:
Extracellular matrix protein implicated in guidance of migrating neurons as well as axons during development, synaptic plasticity as well as neuronal regeneration. Promotes neurite outgrowth from cortical neurons grown on a monolayer of astrocytes. Ligand for integrins alpha-8/beta-1, alpha-9/beta-1, alpha-V/beta-3 and alpha-V/beta-6. In tumors, stimulates angiogenesis by elongation, migration and sprouting of endothelial cells.
Synonyms: TN; TN-C; HXB; MGC167029; 150-225; DFNA56; GMEM; GP; JI
Tractability: Small molecule: a structure with a bound ligand is known. Antibody: a drug acting on it is in phase 2 or 3 trials; its Gene Ontology location is reachable by antibodies, with high confidence; UniProt places it where antibodies can reach, with medium confidence; UniProt predicts a signal peptide or a membrane-spanning region. PROTAC: its protein half-life has been measured.
Gene: Protein-coding gene on chromosome 9 (115,019,575 to 115,118,257, reverse strand). Ensembl gene ENSG00000041982.
Subcellular location: Secreted, extracellular space, extracellular matrix
Pathways (Reactome):
Extracellular matrix organization: ECM proteoglycans; Integrin cell surface interactions; Syndecan interactions
Metabolism of proteins: Post-translational protein phosphorylation; Regulation of Insulin-like Growth Factor (IGF) transport and uptake by Insulin-like Growth Factor Binding Proteins (IGFBPs)
Gene Ontology:
Molecular function: identical protein binding; integrin binding; protein binding; syndecan binding; extracellular matrix structural constituent
Biological process: osteoblast differentiation; regulation of cell adhesion; regulation of cell growth; response to wounding; cell adhesion; regulation of cell migration; morphogenesis of an epithelium; regulation of inflammatory response
Cellular component: extracellular matrix; extracellular region; focal adhesion; membrane; endoplasmic reticulum lumen; perisynaptic extracellular matrix; tenascin complex; basement membrane; interstitial matrix
Genetic constraint (gnomAD): Loss-of-function variants: 105 observed, 203.13 expected, observed/expected ratio (o/e) 0.52, 90% interval 0.44 to 0.61. The upper end of that interval is the gene's LOEUF score, 0.61, which puts it in group 2 of 6, group 1 being the genes least tolerant of losing a copy. Missense variants: 2,713 observed, 2,916.3 expected, observed/expected ratio (o/e) 0.93, 90% interval 0.9 to 0.96. Synonymous variants: 984 observed, 1,129.3 expected, observed/expected ratio (o/e) 0.87, 90% interval 0.83 to 0.92.
Gene-disease validity (ClinGen):
ClinGen rates the evidence that TNC causes each of these diseases.
nonsyndromic genetic hearing loss (autosomal dominant): Limited. A disease characterized by hearing loss that is not part of a larger syndrome.
Homologues: Orthologues: chimpanzee TNC (99% identical), macaque TNC (97% identical), rabbit TNC (90% identical), guinea pig TNC (89% identical), dog TNC (88% identical), pig TNC (87% identical), mouse Tnc (84% identical), rat Tnc (84% identical), tropical clawed frog tnc (54% identical). Paralogues in human: TNXB (38% identical), TNR (28% identical), TNN (21% identical), FN1 (16% identical), ANGPT1 (7% identical), FCN1 (7% identical), FCN2 (6% identical), ANGPTL2 (6% identical), ANGPT2 (6% identical), FIBCD1 (6% identical), FGL2 (6% identical), ANGPT4 (6% identical), and 13 more.
Diseases named in the same sentence as TNC in open-access papers:
TNC is named in the same sentence as 343 diseases in open-access papers, as found by Europe PMC text mining. Sharing a sentence is not in itself a finding about the gene and the disease. The quoted sentences say what the papers report.
breast cancer (139 papers, 1998 to 2025). A primary or metastatic malignant neoplasm involving the breast. "High TNC expression is associated with a poor prognosis in cancers such as glioblastoma, breast cancer and colorectal cancer." (PMID 39754146, 2025). "Studies of the regulation of breast cancer invasion have revealed that specific TNC variants, such as TNC-16 and TNC-14/16, play vital roles in promoting cancer invasion and growth, partly dependent on MMP activity." (PMID 40046232, 2025). "Tenascin-C is a large extracellular glycoprotein which is an important EMT marker in breast cancer and has been implicated in the mechanical properties of both heart and cartilage tissue." (PMID 39974724, 2025). "A gene signature associated with human breast cancer lung metastasis was identified and included key markers such as tenascin C and MMP-2." (PMID 39682261, 2024). "Since the ectopic overexpression of NRP-1 in BT-474 breast cancer cells was associated with the upregulation of tenascin C (TN-C), we next explored this relationship in MDA -231, NRP-1 KO, and NRP-1 Rescue cells using immunofluorescence staining (upper left)." (PMID 37175499, 2023). "TNC is further associated with an elevated expression level in tumor cells and a poor prognosis in several forms of cancer, such as brain tumors or breast cancer." (PMID 37834140, 2023). "Consistent with previous studies, TNC deficiency repressed metastatic colonization by breast cancer cells." (PMID 35469015, 2022). "In breast cancer cells, TNC expression is linked to both the basal subtype and a mesenchymal phenotype." (PMID 35469015, 2022). "In particular, TNC overexpression is positively associated with liver cancer, oral squamous cell carcinoma, and lymph node metastasis of breast cancer." (PMID 32766727, 2020). "High expression of Tenascin-C in breast cancer is associated with increased risk of lung metastases, suggesting that it affects more than proliferative signaling in cancer cells." (PMID 33014869, 2020). "As complementary analysis the oncogenomic portals were used to assess the clinical implication of TNC expression on breast cancer patient’s survival, showing the TNC overexpression associated with a poor survival outcome." (PMID 32817625, 2020). "It appeared that TNC gene mutations measured for 2051 breast cancer patients, are present as somatic mutation only in 11 cases (0.5%)." (PMID 32817625, 2020). "Soluble tenascin-C has been shown to enhance migration and loss of intercellular adhesion in breast cancer cells." (PMID 32340328, 2020). "We found that, similar to SPP1 deficiency, TNC downregulation led to the sensitization of both mammary tumors and lung metastases to paclitaxel treatment." (PMID 30190333, 2018). "Tumor-derived upregulation of TNC was reported to be associated with the aggressiveness of pulmonary metastasis for breast cancer." (PMID 27191989, 2016). "It is less clear, however, what roles THBS1 and TNC-associated signaling have in regulation of chemotherapy resistance in breast cancer." (PMID 27487140, 2016). "The major source of TNC in breast carcinomas is the peri-tumoural stroma, therefore we analysed the effect of fibroblast-associated TNC isoform expression on tumour cell invasion." (PMID 19405959, 2009). "Importantly, the top 4 genes induced by OSM in CAF-173 (SERPINB4, THBS1, RARRES1, and TNC) are associated with decreased overall survival in breast cancer patients." (PMID 35192545, 2022). "Moreover, TGFβ in conjunction with tenascin-C are associated with an epithelial to mesenchymal transition (EMT) of breast cancer cells, and stimulation of macrophages by TGFβ force them to produce type VI collagen." (PMID 33718177, 2021). "The cohort was examined for two CAF-associated proteins with putative prognostic significance: tenascin-C, which has been shown to be up-regulated in a number cancers, and caveolin-1, the loss of which is a strong predictor of overall survival in breast cancer and is a promising marker in NSCLC." (PMID 29416729, 2018).
breast cancer (continued). "Moreover, TNC expression appears to be linked to lung metastasis in breast cancer and leads to a downregulation of tropomyosin-1 and the Wnt inhibitor Dickkopf 1, what in turn results in the destabilization of actin stress fibers and an enhanced Wnt signaling." (PMID 30380741, 2018). "MATN2 and SCGB2A2 are upregulated in ovarian cancer; S100P is upregulated in prostate cancer, invasive ductal carcinomas, and pancreatic cancer; LDHB is a biomarker for triple negative breast cancer; and TNC is associated with Tamoxifen resistance in breast cancer." (PMID 27449296, 2016). "We therefore concluded our study by investigating whether the genes co-regulated with tenascin-C would also be implicated in breast cancer progression." (PMID 24495796, 2014). "Tenascin C has been described to increase lung metastasis and to promote the survival of breast cancer cells forming pulmonary micrometastases." (PMID 40017592, 2025). "CAFs secrete Tenascin-C, which reduces breast cancer cell apoptosis and aids in metastatic foci formation." (PMID 40230452, 2025). "While this study focused on breast cancer, the similar down-regulation in chondrosarcoma suggests a potential parallel mechanism, implicating TNC in chondrosarcoma progression." (PMID 38542153, 2024). "Tenascin C was shown to promote breast cancer cell infiltration into the lung and to support the metastasis-initiating ability of these tumor cells." (PMID 39682261, 2024). "Under the chemotherapy, JNK pathway activation triggers osteopotin (or SPP-1) and TNC secretion, then induces chemoresistance and metastasis in breast cancer." (PMID 36906534, 2023). "TNC is expressed in many primary tumor types and proteomic analyses have shown that TNC is a very abundant ECM protein in the stroma of solid tumors including breast cancer, PDAC and lung cancer." (PMID 37098922, 2023). "Here, we study the interplay between the matrix molecule tenascin-C (TNC) and chemokine CCL2, both elevated in and associated with the progression of breast cancer and playing key roles in myeloid immune responses." (PMID 37176074, 2023). "To assess any association between the expression of TNC and CCL2, we analyzed RNA sequencing data from 77 HER2+/ERBB2+ breast cancer patients available from The Cancer Genome Atlas." (PMID 37176074, 2023). "Stimulation with transforming growth factor β1 (TGF-β1), metastatic breast cancer conditioned media (CM), or tenascin-C activated these hydrogel-encapsulated HLFs in a manner reflective of their native in vivo responses." (PMID 36865293, 2023). "Others, such as COL18A1, TGFBI, FGB, ITIH2, ITIH4, and TNC among others, were overrepresented in 3 of 4 signatures and also expressed in mammary carcinoma xenografts." (PMID 37098922, 2023). "In breast cancer, the expression of TNC is correlated with the aggressiveness of pulmonary metastasis." (PMID 35260891, 2022). "In vitro experiments suggested that tenascin-C can induce epithelial-to-mesenchymal transition (EMT) in breast cancer cells via binding to αvβ6 and αvβ1 integrins, colorectal and pancreatic cancer cells or promote invadopodia formation in Ewing sarcoma." (PMID 35008401, 2022). "Inhibition of JNK signalling or down-regulation of SPP1 or TNC can sensitise mammary tumours to chemotherapy and suppress the progression of metastatic breast cancer." (PMID 35260891, 2022). "TNC is abundantly expressed in a variety of tumors, including breast cancer, colon adenocarcinoma, prostatic adenocarcinoma, and lung carcinoma, but particularly in gliomas." (PMID 36033448, 2022). "TNC is a matrix glycoprotein expressed by breast cancer cells as a crucial niche component and promoter of lung metastasis." (PMID 35469015, 2022). "The ECM protein tenascin C (TNC) secreted from breast cancer cells arriving in the lung initiates the formation of a metastatic micro‐niche." (PMID 35506376, 2022).
breast cancer (continued). "For example, tenascin C induces EMT in breast cancer cells, endoglin regulates EMT in renal cell carcinoma, carbonic anhydrase IX promotes EMT in prostate cancer cells, and osteopontin has been credited as a master regulator of EMT." (PMID 36012449, 2022). "TNC promotes breast cancer lung metastasis primarily by activating TGF-signaling, which improves cell plasticity, angiogenesis, cell survival, and migration." (PMID 36421704, 2022). "Whilst we showed that tumor-derived tenascin-C drives M2 macrophage polarization in experimental mammary tumors, contradictory findings to ours have been found in glioblastoma." (PMID 33718177, 2021). "Recently, we used an orthotopic grafting murine model of breast cancer to demonstrate that the tumor-derived tenascin-C is able to switch the phenotype of TAM towards a M2-like, pro-tumoral polarization, in a FBG/TLR4 dependent fashion." (PMID 33718177, 2021). "When co-cultured with breast cancer cells, ADSCs would differentiate into cancer-associated fibroblast-like myofibroblastic phenotype, namely CAFs, express α-SMA and tenascin-C, and promote angiogenesis and cell invasion in breast cancer." (PMID 33407902, 2021). "TNC− and TNC+ groups almost equally distributed between breast cancer subtypes except for Her2+ breast cancer specimens where the TNC+ phenotype was more prominent (41%) than the TNC− phenotype (29%)." (PMID 33988305, 2021). "Together, these studies demonstrate that in breast cancer, there is a correlation between changes in expression levels of ECM molecules such as hyaluronan, collagen, fibronectin or tenascin-C with intratumoral TAM density, linked to disease outcome." (PMID 33718177, 2021). "In breast cancer, CAFs-derived tenascin C and VEGFA are the key molecules involved in metastasis to the lung." (PMID 34572878, 2021). "The lysine-specific demethylase JARID1A, upregulates the expression of the extracellular matrix protein Tenascin C (TN-C), and favors breast cancer cell invasion." (PMID 33803458, 2021). "In breast cancer metastasis, endothelial tip cells within the perivascular niche deposit increased levels of periostin, tenascin-C, versican, S100 proteins, TGFβ and MIF, which act to maintain cancer cell dormancy." (PMID 33014869, 2020). "In approach with ATN-RNA, it seems that TNC in breast cancer cell line plays an anti-adhesive role, which would affect the cell migration and invasion ability in addition to EMT processes." (PMID 32817625, 2020). "The high expression level has a great impact on the shorter survival for the patients, thus suggesting also that TNC can be also considered as the prognostic factor for breast cancers (P = 0.0196)." (PMID 32817625, 2020). "We found that down-regulation of TNC expression by ATN-RNA significantly impaired the cell migration in breast cancer cell lines." (PMID 32817625, 2020). "Tenascin C (TNC), an extracellular matrix protein expressed in stem cell niches of breast cancer, supports pulmonary metastasis." (PMID 32448364, 2020). "The data on the mRNA and protein level, although differ in the number of the samples, still keep, in our mind, the tendency which shows the overexpression of TNC in breast cancer samples." (PMID 32817625, 2020). "In order to investigate the involvement of TNC on breast cancer cells proliferation, MDA-MB-231 cell line was treated with ATN-RNA and the real-time cell proliferation assay was performed." (PMID 32817625, 2020). "The results show that the ATN-RNA transfected cells lose their ability to migrate, thus showing the involvement of TNC in breast cancer invasiveness." (PMID 32817625, 2020). "Tenascin-C-mediated breast cancer cell reprogramming inhibits JAK2-STAT5 signaling to enhance MSI1 expression and drive pro-metastatic NOTCH signaling." (PMID 33014869, 2020). "TNC is one of the main protein overexpressed in breast cancer, indicating a role for this ECM molecule in cancer pathology." (PMID 32817625, 2020).
breast cancer (continued). "Different studies verified a correlation between Tenascin-C expression and prognosis in different cancer types, like chondrosarcoma as well as prostate and breast cancer." (PMID 32560557, 2020). "Closely mimicking the tumor environment 3D cell line spheroids model of breast cancer confirmed TNC direct involvement in tumor spheroids viability, thus the down-regulation of this protein results in disintegration of spheroid morphology." (PMID 32817625, 2020). "In human breast cancer cells, αvβ6 and αvβ1 integrins mediate tenascin-C-induced EMT through a pathway that involves FAK phosphorylation and Src activation, a decrease in E-cadherin expression, and increased cell migration." (PMID 32340328, 2020). "We first compared the expression level of tenascin-C in 4 subtypes of breast cancer using GEPIA program." (PMID 32817625, 2020). "Tenascin C is another example of an ECM protein secreted by breast cancer metastatic cells to create a supportive niche in the lungs." (PMID 31330946, 2019). "In breast cancer, TNC expression in the invasive border of the tumor is regarded as a predictor of local and distant recurrence." (PMID 31632476, 2019). "Tenascin C induces epithelial-to-mesenchymal transition (EMT) changes in breast cancer cells and promotes their survival and outgrowth at secondary organs, such as the lung." (PMID 30674353, 2019). "The correlation between expression of the extracellular matrix glycoprotein tenascin C and breast cancer metastatization to the lung has been reported, with tumor-related tenascin C being essential in early phases of metastatic onset." (PMID 31330946, 2019). "TNC expression in breast cancer animal model, initiated lung metastasis by enhancing WNT and NOTCH signaling and enhancement of stem cell signaling components, EMT-like phenotype in colorectal cancer and angiogenesis in lung cancer." (PMID 31798767, 2019). "TNC was reported to play an important role in dedifferentiation and metastasis of breast cancer and lung cancer." (PMID 31798767, 2019). "Our results reveal that SPP1 and TNC are directly induced by the c‐Jun transcription factor in breast cancer cells in response to stress and serve as essential mediators of chemotherapy resistance." (PMID 30190333, 2018). "We find that deficiency of either SPP1 or TNC, or inhibition of upstream JNK signaling, impairs experimental mammary tumor progression to metastasis." (PMID 30190333, 2018). "Recently, TNC was shown to activate epithelial to mesenchymal transition in breast cancer cell lines, further suggesting it has a strong influence on cell signaling during tumor progression." (PMID 30154546, 2018). "Considering this, we evaluated the clinical relevance of SPP1 and TNC expression in tumors, by analyzing transcriptomic profiles from breast cancer patients that were annotated for lung metastasis." (PMID 30190333, 2018). "Our study in the BT-474 breast cancer model provides further insight into this pathway by highlighting the role of NRP-1 in triggering ITGB3/FAK/Akt-473 in a TNC-dependent pathway to trigger cell migration." (PMID 29728077, 2018). "This is in part due to a recent report that demonstrated that stromal deposition of tenascin-C from fibroblasts co-cultured with breast cancer cells occurred exclusively in the presence of a pre-established cell-derived fibronectin matrix." (PMID 28187162, 2017). "Likely, breast cancer cell-derived tenascin C (TNC) promotes the survival and outgrowth of pulmonary micrometastases." (PMID 29197379, 2017). "Tenascin C, an essential factor in the aggressiveness of pulmonary metastasis of breast cancer, is also more highly expressed in tumorspheres than in monolayer cultures of breast cancer cells." (PMID 28423353, 2017). "Components of the ECM such as tenascin C have been shown to promote breast cancer progression and metastasis." (PMID 28103946, 2017).